CXCR4 (C-X-C motif chemokine receptor 4)
Diseases named in the same sentence as CXCR4 in open-access papers (continued):
Sharing a sentence is not in itself a finding about the gene and the disease.
tumor (continued). "MIF exerts its effects through interaction with CD74, CXCR2 and CXCR4 found on MDSCs and tumour cells." (PMID 33803414, 2021). "Several recent studies have shown that SDF-1/CXCR4 pathway can play an important role in the progression of tumor." (PMID 33906294, 2021). "Increased CXCR4 expression on tumor cells also leads to invasion, migration and epithelial-mesenchymal transition (EMT) of HCC cells." (PMID 34386499, 2021). "Here, similarly to HSC recruitment, CXCL12/CXCR4 signaling is one of the main stimulatory axes attracting CTCs to home to and to adhere within bone, and also supports tumor cell survival and dormancy as well as angiogenesis." (PMID 34064859, 2021). "One group recently used CXCR4, which is enriched in BCBMs, to target poly(lactone-co-β-amino ester) NPs to tumor cells." (PMID 34716900, 2021). "The increase in CXCR4 triggers actin polymerization, pseudopodia formation, and induces the targeted migration and invasion of tumor cells." (PMID 34539883, 2021). "This is used by the SDF-1/CXCR4 axis to inhibit apoptosis and promote tumor cell growth and proliferation." (PMID 33980216, 2021). "CXCR4 expression is elevated in tumor cells, and high levels of CXCL12 are expressed in tumor metastases target tissues such as lung, liver, brain, and bone." (PMID 33390169, 2021). "Mechanistically, up-regulated CXCR4 expression on endothelial cells is mediated by the ERK pathway induced by inflammatory cytokines derived from tumor conditioned monocytes/macrophages." (PMID 34386499, 2021). "Tumours containing TASCs overexpressing syndecan‐2‐peptide also had lower levels of CXCR4 and PD‐L1 expression, indicating a less immunosuppressive environment." (PMID 33152121, 2021). "In malignancies, CXCR4 has been shown to be overexpressed as compared to non-malignant control tissue and, moreover, to be associated with adverse prognosis in many different types of cancer, suggesting a role of CXCR4 as a tumor driver." (PMID 34417915, 2021). "Cell signaling pathways and secretory factors including TGF-β, IGF-1, Notch, IL6, CXCR4, and PTHrP contribute to tumor growth in the bone microenvironment." (PMID 34503118, 2021). "More importantly, largely present in control tumors, macrophages were even more abundant upon CXCR4 inhibition, now clearly infiltrating the tumor nests (and EV5G)." (PMID 33988305, 2021). "In the dedifferentiated tumor cell lines used in our experiments, Wnt inhibitors inhibited CXCR4 expression and function while Wnt activation had the opposite effect." (PMID 33671498, 2021). "Meanwhile, in patient 1, tumor piece 2 pronouncedly high AQP1 expression correlates with high CXCR4 and HIF expression, in patient 3, a higher or lower AQP1 expression does not correlate with CXCR4 expression." (PMID 33467498, 2021). "We determined 25 of 100 tumor tissues showed high CXCR4 IHC staining in the cytoplasm of cancer cells." (PMID 34804954, 2021). "Collectively, our data demonstrate that orthotopic PCa tumour-derived ALDH+CD44+CXCR4+CD24+ cell compartment is a maintainable subpopulation of pluripotent PCSCs with more tumorigenic and metastatic potential than other isogenic PCa cells." (PMID 34247196, 2021). "NF-κB-promoting proinflammatory mediators, associated with tumor growth and antiapoptotic molecules (i.e.,MMP-9, CXCR4, Ki-67, β1-integrin, and Caspase-3) and its translocation to the nucleus in HCT116 cells, were increased in both TME cultures." (PMID 34660256, 2021). "In the present study, we interestingly found that tumor-infiltrating pDC were highly present in OSCC tissues expressing high levels of CXCR-4." (PMID 33854604, 2021). "CXCR4 leads to enhanced proliferation, migration, and invasion of tumor cells by binding to CXCL12 and activating various downstream signaling pathways." (PMID 35111153, 2021). "Overall, it showed promising results with respect to CXCR4 imaging in tumor models, and further studies are needed to ascertain its reliability." (PMID 34500609, 2021).
tumor (continued). "Overexpressed in the cancer stem cells of more than 20 human neoplasias, CXCR4 is a convenient antitumoral drug target." (PMID 34834337, 2021). "SOX4 has been suggested to promote tumor angiogenesis through CXCR4 and endothelin-1 in breast and hepatocellular tumors, respectively, in 2 recent studies." (PMID 34228647, 2021). "In the 7‐week model, we observed a reduced tumor weight in AMD‐treated mice, indicating that inhibition of CXCR4 reduced tumor growth." (PMID 33988305, 2021). "This therapy-induced tumor infiltration with CXCR4-expressing immune cells was efficiently inhibited by daily administration of AMD3100 on the days following irradiation." (PMID 34885030, 2021). "Recent studies have shown that CXCL12 is produced by stromal cells, secreted in the TME, and binds to CXCR4 on the surface of tumor cells, which is crucial for tumor metastasis and poor prognosis 5-7." (PMID 33854601, 2021). "Herein, we discuss the current understanding on the role of CXCL12/CXCR4/CXCR7 cross-talk in tumor progression and immune cells recruitment providing support for a combined CXCR4/CXCR7 targeting therapy." (PMID 33937018, 2021). "Its involvement in tumor metastasis has been proven in different tumors, in which CXCR4 expression promotes the migration and metastasis of tumor cells into tissues with increased levels of CXCL12." (PMID 34575965, 2021). "Higher c-MYC and CXCR4 expression was detected in polyp and tumor swab samples compare to normal, whereas expression of CD26 showed in CRC samples is reduced, in comparison to normal and polyp samples." (PMID 34335790, 2021). "The CIBERSORT algorithm was used to further explore the correlation between tumor-infiltrating immune cells (TIICs) and CXCR4." (PMID 34568309, 2021). "Paclitaxel treatment significantly (p < 0.05) reduced the growth of tumors having CXCR4 knockdown cells as compared to control tumor-bearing animals treated with paclitaxel." (PMID 33966046, 2021). "We designate this mechanism “Immunogenic Surrender” because the tumor cells surrender to macrophages in response to CXCR4 activation, which generally promotes their growth and dissemination." (PMID 33956406, 2021). "Beyond its pre-eminent role in the context of tumor cell growth as well as metastasis, the C-X-C motif chemokine receptor 4 (CXCR4) is a key player in the orchestration of inflammatory responses to inflammatory stimuli." (PMID 34885030, 2021). "AMD3100, a highly specific CXCR4 antagonist, has a synergistic effect with anti-PD-1 antibody in tumor treatment." (PMID 35003065, 2021). "Of these, the protein levels in the refractory PCa tissues were the highest, suggesting the presence of ALDH+CD44+CXCR4+CD24+ tumour cells in human PCa tissues." (PMID 34247196, 2021). "In tumors, CXCR4 is overexpressed in circulating neutrophil subsets, which promotes angiogenesis and tumor progression." (PMID 33996815, 2021). "Inhibiting CXCR4 inhibits tumor growth, reduces lung metastasis, and improves survival after sorafenib treatment." (PMID 33771976, 2021). "DPP-4 inhibitor-induced breast cancer metastasis was attenuated by the CXCR4 inhibitor AMD3100, with the suppression of genes associated with EMT and a mammalian target of rapamycin (mTOR) signaling pathway in the primary tumor." (PMID 34063285, 2021). "Fluorescence quantification showed a 4-fold higher expression of CXCR4 in the U2932 tumors relative to SuDHL8 (p<0.001); this was further confirmed by western blot analysis of tumor lysates." (PMID 34793563, 2021). "In vivo and in vitro experiments show that AMD3100, a CXCR4 antagonist, targets the CXCR4/stromal cell-derived factor-1 axis by competitively binding CXCR4 to inhibit the proliferation and invasion of tumor cells." (PMID 34504845, 2021). "Numerous studies have shown that SDF-1/CXCR4/β-catenin signalling is significant in tumour metastasis." (PMID 33637678, 2021).
tumor (continued). "Previous studies have reported that the specific binding of the SDF-1/CXCR4 axis can activate the phosphorylation of a variety of downstream pro-tumor survival signaling pathways." (PMID 34733839, 2021). "Further examination revealed that CXCR4 expression was concentrated in CD205+ subsets of tumor‐induced G‐MDSCs." (PMID 34646521, 2021). "Whereas different organs can attract CXCR4-expressing tumor cells, CCR7 expression is mainly a prerequisite for dissemination to secondary lymphoid organs." (PMID 34503058, 2021). "Recently, the chemokine CXCL12 and its receptor CXCR4 have emerged as promising drug targets due to their crucial roles in the tumor microenvironment and trafficking of immune cells." (PMID 33456563, 2021). "CXCL12 recruits CXCR4+ BMDCs to the tumour, including vascular progenitor cells that can differentiate and incorporate into new blood vessels, but also MMP-9-expressing myeloid cells that indirectly regulate tumour angiogenesis." (PMID 33803414, 2021). "The present study proposes a tumor-promoting role of CD8Low ST2L+ regulatory T lymphocytes via effects of CXCR4-enhancing S1P4 receptor signaling, which is in accordance with current concepts of anti-cancer immunotherapy." (PMID 34504486, 2021). "In this thesis, we identified that CXCR4 expression was prominently correlated with tumour location, clinical staging, histological subtype, implication of resection margin, tumour relapse and metastasis." (PMID 34170080, 2021). "Then, monocytes differentiate into migratory TAMs and C-X-C chemokine receptor type 4 (CXCR4) expression by TAMs is then promoted by tumor-derived transforming growth factor-β (TGF-β)." (PMID 33783686, 2021). "The CXCL12/CXCR4 axis constitutes one of the most important signaling pathways that regulates tumor growth, angiogenesis, and metastasis, and it is a predictive factor for survival in patients." (PMID 33530455, 2021). "The CXCL12 receptors, CXCR4 and CXCR7, are also overexpressed within GSCs 135, 136, and the CXCR4 inhibitor AMD3100 reduced GSC-mediated tumor growth and angiogenesis in association with lower VEGF production." (PMID 33391498, 2021). "The SDF-1/CXCR4 signaling pathway promotes the development of HCC by facilitating tumor growth, angiogenesis, and HCC metastases." (PMID 33889573, 2021). "The downregulation of CXCR7, which would increase migration/metastatic potential of tumor cell, is lost due to the counterbalance of CXCR4." (PMID 33808801, 2021). "Analysis of CXCR4 expression on excised tumor tissues corroborated the large differences in receptor expression between the two models." (PMID 34793563, 2021). "Reasonable to high tumor/background ratios and CXCR4-specificity of tumor uptake were found for several novel ligands." (PMID 34885030, 2021). "Nevertheless, more experimental research is warranted to explore the underlying molecular mechanisms and potential clinical value of CXCR4 for the early diagnosis of tumor micrometastasis." (PMID 34568309, 2021). "Recent studies have shown that several cancer types including breast and prostate overexpress the corresponding receptor CXCR4 providing a mechanism for the homing of tumor cells to the bone microenvironment." (PMID 34503118, 2021). "The C-X-C chemokine receptor type 4 (CXCR4)/stromal-derived factor-1 (SDF-1) axis is also involved in the recruitment of MSCs to the tumor site." (PMID 33445681, 2021). "Another possibility to improve CAR NK cell function is to overexpress the chemokine receptor CXCR4 to promote migration to the tumor site." (PMID 34804035, 2021). "In summary, these studies show that AMD3100 is able to successfully inhibit crucial tumor-driving effector mechanisms of CXCR4/CXCL12 signaling in vitro and in vivo." (PMID 34203660, 2021). "A high expression of CXCR4 in BrCa and PrCa tissue or tumor cells significantly correlates with distant lymph node, lung, and bone metastases, and increased aggressiveness." (PMID 34064859, 2021).
tumor (continued). "The binding of CXCR4 to its ligand SDF-1 (CXCL12) stimulates tumor cell proliferation and migration by activating downstream signaling transduction pathways, including the PI3K-AKT and MAPK pathways." (PMID 34503103, 2021). "In the formation of the pre-metastatic niche, the SDF-1α/CXCR4 axis contributes to the recruitment of endothelial progenitors (EPCs) to the tumour microenvironment." (PMID 33919589, 2021). "We designate as Immunogenic Surrender the process by which CXCR4 turns in tumor cells to macrophages, thereby subjecting a rapidly growing tissue to immunological scrutiny." (PMID 33956406, 2021). "The CXCR4-inhibitors a promising class of anti-tumor agents that should be further explored in clinical trials." (PMID 34220311, 2021). "miR-126 can also inactivate the RhoA signaling pathway in colon cancer by reducing the expression of CXCR4 and inducing a tumor suppressor effect." (PMID 34447750, 2021). "The SDF1/CXCR4 complex has been suggested to be involved in many cellular functions, including embryogenesis, immune surveillance, inflammation, tumor growth, and metastasis." (PMID 33953165, 2021). "In conclusion, we successfully developed a T140-MB that can be used for imaging CXCR4 expression in the tumor vasculature." (PMID 34793563, 2021). "CXCL12 promoter hypermethylation downregulates CXCL12 protein expression in PC, disrupting the cellular feedback internalization of membranous CXCR4 and so favoring tumor cell motility and metastatic potential." (PMID 34830196, 2021). "Tumor-associated neutrophils are able to release CXCR4, VEGF and MMP-9 to promote tumor bone metastasis." (PMID 34831167, 2021). "In this study, the H-bMSCs exhibited tumor homing ability based on the CXCR4/SDF-1α axis and the effect of inflammatory regulation in the TME." (PMID 34069607, 2021). "We further found that the interference of the expression of CXCL12 receptor CXCR4 in tumor cells inhibited DLBCL tumor cell migration." (PMID 34093792, 2021). "CXCR4 inhibition also increased the number and infiltration of activated macrophages whereas tumor‐promoting M2 macrophages disappeared." (PMID 33988305, 2021). "One future candidate for an even more precise N- and M-staging is the chemokine receptor CXCR4 and its radiolabeled ligand [68Ga]pentixafor which addresses tumor growth, invasiveness and metastasis." (PMID 34292419, 2021). "The high expression of CD44 in hypoxic tumor regions is plausible because hypoxia promotes CXCR4-mediated cell homing 42-44." (PMID 34093792, 2021). "From this we conclude that approximately 55% of cells in 3D Matrigel cultures are VIM+/CXCR4+ presumptive tumor cells, and approximately 10% are VIM+/CXCR4− presumptive fibroblasts." (PMID 34884982, 2021). "The interaction between SDF-1 and CXCR4 is shown to modulate normal hematopoiesis but also mediate homing and engraftment of the tumor cells in the BM." (PMID 34395425, 2021). "Altogether, these results suggest that reduced metastasis is likely due to a major impact of CXCR4 inhibition on tumor growth." (PMID 33988305, 2021). "These pathways are exploited during tumorigenesis, especially in the metastatic process, where CXCR4-expressing tumor cells are chemotactically homed to organs with abundant levels of CXCL12—such as the liver, bone marrow, lungs and lymph nodes." (PMID 34793563, 2021). "Circulating tumour cells leave the blood vessels as a result of the interplay between SDF-1α and CXCR4, which leads to metastatic tumour formation." (PMID 33919589, 2021). "Inoculation with 102 or 103 ALDH+CD44+CXCR4+CD24+-PCa cells produced the greatest tumour mass within the shortest time, as compared with three other sorted subpopulations." (PMID 34247196, 2021). "We further assessed the effects of CXCR4 by examining in vivo tumor growth and metastasis/invasion of LLC1 cells upon combining CDDP and AMD3100 treatment." (PMID 33953165, 2021).
tumor (continued). "MSCs were primed with trichostatin A under hypoxia, which upregulated the expression of CXCR4, a chemokine receptor involved in tumor tropism, and coxsackievirus and adenovirus receptor that plays an important role in adenoviral infection." (PMID 34068264, 2021). "Together, these data indicate that MSCs primed by TSA not only increase CXCR4 expression, but also enhance tumor tropism in vitro." (PMID 34068264, 2021). "Meanwhile, ADSC-secreted soluble factors, e.g., VEGF, G-CSF, and SDF-1alpha/CXCR4, synergistically contribute to the formation of a proinflammatory tumor microenvironment, thus facilitating tumor growth." (PMID 33505474, 2021). "Expression of CXCR4, a chemokine (C-X-C motif) receptor that plays a central role in tumor growth and metastasis of circulating tumor cells, has been described in a variety of solid tumors." (PMID 33579381, 2021). "The C-X-C chemokine receptor 4 (CXCR4) is G protein-coupled receptor that upon binding to its cognate ligand, can lead to tumor progression." (PMID 34793563, 2021). "The multi-step transformation of tumor cell malignancy involves pluripotency reprogramming, and CXCR4 is reportedly involved in cell pluripotency that triggers cell renewal, chemotaxis, and re-differentiation, in a cancer niche." (PMID 34070538, 2021). "Key players in tumor progression, metastasis and survival are the receptor CXCR4 and its ligand CXCL12." (PMID 35111484, 2021). "This process is fostered by the overexpression of specific chemokine receptors in bone-homing tumor cells, namely C-X-C motif chemokine receptor 4 (CXCR-4), which is normally expressed in hematopoietic stem cells (HSCs)." (PMID 34360979, 2021). "Majority of aberrantly expressed miRs targeting CXCR4 in a wide range of cancers are tumor suppressors, for example, in CRC miR-126, miR-133b, miR-193a-5p, and miR-622 are tumor suppressors, whereas miR-125b is the only overexpressed onco-miR." (PMID 34298991, 2021). "Taken together, our study suggests that Salmonella is sufficient to inhibit primary tumor growth and CXCR4-dependent migration and metastasis in vivo." (PMID 34220311, 2021). "And it was also found that CD8+ T cells are fewer in PAAD than in paracancerous tissues and that the combination of PD-1 and CXCR4 results in an increase of CD8+ T cells in tumor tissues to promote tumor cell apoptosis." (PMID 34760926, 2021). "Doxycycline fed groups (CXCR4 overexpression) resulted in significant (p < 0.05) induction of tumor volume and weight as compared to the control group." (PMID 33966046, 2021). "We further demonstrated that knockdown of CTNND1 not only enhanced intrinsic metastatic functions including migration and invasion, but also facilitated tumor recruitment to bones, an event through the CXCR4/CXCL12 axis by activating PI3K/AKT/HIF-1α pathway." (PMID 34830862, 2021). "The therapeutic effects were most likely due to the targeting both of tumor hypoxia and CXCR4 by combining losartan, AMD3100, with local irradiation." (PMID 33663521, 2021). "Currently, the promotion of bMSCs migration to tumor is mainly achieved through the CXCR4/SDF-1α axis, which are thought to be the most important pair of cytokines." (PMID 34069607, 2021). "As expected, the miR-588 expression was up-regulated and CXCR4 expression was down-regulated by circABCB10 knockdown in the tumor tissues of the mice." (PMID 34015764, 2021). "In SS patients, the impaired expression of CD26 on tumor cells was responsible for uncontrolled accumulation of CXCR4+ T cells in the skin where CXCL12 is abundantly expressed." (PMID 34503058, 2021). "Expression of CXCR4 as a marker for metastatic homing cannot be widely observed but is present in some tumor cells." (PMID 33671521, 2021). "In their study, they encapsulated Rh-188 and a CXCR4 blocking antibody (12G5) in a lipophilic nanoparticle which, upon delivery to tumor cells, targets CXCR4 and exposes it to radiotherapy." (PMID 34203660, 2021).